AR (androgen receptor)
Diseases named in the same sentence as AR in open-access papers (continued):
Sharing a sentence is not in itself a finding about the gene and the disease.
prostate carcinoma (continued). "To understand the biology of prostate cancer, we have to appreciate the role of the androgen receptor signaling in the development, function, and homeostasis of the prostate." (PMID 24213111, 2011). "For example, AR- P63-CD44+Nestin+ HPET-5 cells were purified from prostate cancer cell lines and shown to recapitulate prostate-like structures in the mouse kidney after transplantation." (PMID 21241512, 2011). "There is ample evidence in the literature that prostate cancer growth can be inhibited by blocking the AR." (PMID 22111003, 2011). "Activated Ack1 has been shown to phosphorylate and activate AR function and to promote the progression of prostate cancer." (PMID 21637378, 2011). "We believe this course of prostate cancer cell differentiation is also controlled under androgen/AR regulation, which just mimics the normal epithelial cell hierarchical lineage." (PMID 21754978, 2011). "Since prostate cancers are dependent on androgens for development, growth and survival, inhibition of AR activity is a major therapeutic goal for management of the disease." (PMID 21935435, 2011). "In one recently described model, cell fractionation studies of CWR22 human prostate cancer xenograft tumors demonstrated that tumor protospheres containing CK8+/CK5+/AR-/TP63- cells gave rise to CK8+/CK5-/AR+ tumors." (PMID 22022528, 2011). "It is known that androgen and AR are involved in all stages of prostate cancers including initiation, progression, and treatment resistance, suggesting that AR signaling contributes to anti-apoptotic mechanism." (PMID 22200028, 2011). "Accumulating evidence suggests that the androgen receptor (AR) plays a critical role in regulating the growth of both androgen-sensitive and androgen-refractory prostate cancer." (PMID 22164169, 2011). "AR is essential for the growth and survival of prostate cancer cells and is therefore a target for current and next-generation therapeutic modalities against prostate cancer." (PMID 21909421, 2011). "In the AR-dependent pathway, AR function is often converted from a growth suppressor to an oncogene stimulating prostate cancer cell survival and proliferation." (PMID 20628607, 2010). "It has been shown that prostate cancer resistant to androgen withdrawal therapies still contains AR with maintained role in proliferation of hormone-refractory prostate cancer cells." (PMID 20535283, 2010). "Although DHT, acting through the AR, is essential for the growth of prostate cancer, the mechanism of androgen-stimulated cell proliferation has not been fully defined." (PMID 20102617, 2010). "Our earlier studies demonstrated that Ack1 regulates prostate cancer progression to androgen independence by positively regulating androgen receptor (AR) and negatively regulating the tumor suppressor, Wwox." (PMID 20333297, 2010). "Levels of the androgen receptor (AR) expressed in the luminal epithelium usually increase in the nucleus during human prostate carcinoma progression." (PMID 20585617, 2010). "The protective effects of cruciferous vegetables consumption against prostate cancer appears to be partially related to the potential ability of ITCs to interact with the AR signaling pathway." (PMID 22069601, 2010). "The findings showed that CARM1 was generally underexpressed in prostate cancer cells excluding PC3 and DU145, AR-deficient cells." (PMID 20462455, 2010). "Knockout of the miR processing enzyme, DICER, in LNCaP prostate cancer cells or tissue specifically in mice inhibited AR function leading to AIS." (PMID 21048966, 2010). "The androgen-signaling pathway, mediated mostly through the androgen receptor (AR), plays a critical role in the regulation of prostate cancer cell growth and survival." (PMID 20946682, 2010). "Our results suggest that the study of the potential link between menin and AR expression or activity in prostatic cells would be of great interest, as the latter is deregulated in the prostate cancers found in Men1 mutant mice." (PMID 20663219, 2010).
prostate carcinoma (continued). "Our previous study showed that expression of c-Met in prostate cancer cells was increased after attenuation of androgen receptor (AR) signalling." (PMID 20946682, 2010). "It is generally considered that AR expression in prostate cancer cells reflects not only the differentiation status of the cells, but also their sensitivity to anti-AR treatment." (PMID 20663219, 2010). "Androgen ablation therapy is a viable treatment modality for patients with primary hormone (androgen)-dependent prostate cancer, lowering the serum androgen level and blocking androgen receptor (AR)-mediated signal transduction." (PMID 20102617, 2010). "Prostate cancer is a common and heterogeneous disease, where androgen receptor (AR) signaling plays a pivotal role in development and progression." (PMID 20140206, 2010). "AR and Wwox Tyr-phosphorylations appear to be involved in late stage progression of prostate cancer to androgen-independence." (PMID 20333297, 2010). "Next, we further assessed the effect of the c-Met inhibitors on other AR positive prostate cancer cell lines, including LAPC4, LNCaP C4-2B, and CWR22Rv1." (PMID 20946682, 2010). "Inhibition of AR expression by AR siRNA also suppressed the translocation of exogenous HA-Bax, thereby inhibiting HABax-induced apoptosis in prostate cancer cells." (PMID 20831839, 2010). "Suggested models of CRPC involve: the AR; steroid synthesis and metabolism; neuroendocrine prostate cancer cells; and/or an imbalance of cell growth and cell death." (PMID 20868494, 2010). "Recent studies revealed a connection between the AhR pathway and prostate cancer both in vitro and in vivo, showing that the AhR interacts and inhibits the AR." (PMID 20140206, 2010). "This review covers the possible roles of two ROS-induced transcription factors, Nrf1 and Nrf2, and the antioxidant proteins peroxiredoxin-1 (Prx-1) and Thioredoxin-1 (Txn-1) in modulating AR expression and signaling in aggressive prostate cancer (PCa) cells." (PMID 24281119, 2010). "It is likely that cancer-specific alterations of the AR that affect the spatial kinetics of DNA binding and cofactor recruitment play a role in prostate cancer progression and its response to treatment." (PMID 20406442, 2010). "ERBB2 has been shown to stabilize AR protein in prostate cancer cells and to activate the Akt pathway." (PMID 20712882, 2010). "First, PTEN has been shown to inhibit androgen receptor-driven transcription in LNCaP prostate cancer cells in an AKT-dependent or independent manner." (PMID 20712882, 2010). "Most untreated prostate cancers retain some dependence upon the AR and respond, at least transiently, to androgen ablation therapy." (PMID 20406442, 2010). "Recently several in vitro studies also demonstrated that SF interacts with the AR pathway reducing prostate cancer survival." (PMID 22069601, 2010). "The AR is suspected to continue to play an important role in the hormonal progression of prostate cancer." (PMID 20868494, 2010). "While this is not proven in humans, it is quite intriguing and further supports the relevance of MYC-based prostate cancer models driven by AR as highly relevant to the human disease." (PMID 20195545, 2010). "Most clinical prostate cancers are AR-dependent, and this observation has motivated androgen ablation therapy." (PMID 20406442, 2010). "Recently, we demonstrated that AR suppressed c-Met transcription and that increased c-Met expression was induced by removal of androgens in prostate cancer cells." (PMID 20946682, 2010). "A recent study in prostate cancer cells indicated that CASP8 plays a pathway specific role in inhibiting androgen receptor signaling." (PMID 20132554, 2010). "Accordingly, we investigated the potential effect of BFA on androgen-mediated prostate cancer cell growth, focusing on the cell cycle and AR regulation in androgen-responsive prostate cancer LNCaP cells." (PMID 20102617, 2010).
prostate carcinoma (continued). "IL-8 has been shown to increase the transcriptional activity of the androgen receptor in prostate cancer cell lines, suggesting a potential role of this chemokine in modulating the transition of prostate cancer to an androgen-independent state." (PMID 20420679, 2010). "To check for AR interaction, we used the androgen-responsive prostate cancer cell LNCaP which have high levels of AR." (PMID 20210997, 2010). "Using an AR positive, androgen insensitive prostate cancer cell line, LNCaP C4-2, we showed for the first time that PF-2341066 inhibited the growth of AR positive prostate tumor xenografts in vivo." (PMID 20946682, 2010). "We have also mentioned that the AR/PSF complex interacts with the PSA gene (perhaps the most well-established prostate cancer biomarker) and that SFPQ/PSF inhibits AR transcriptional activity." (PMID 20805891, 2010). "Targeting AR by SFN is a therapeutically viable strategy for the treatment of prostate cancer since AR is the central protein in prostate cancer signaling." (PMID 20976254, 2010). "E006AA cells represent a third new subtype of AR-expressing prostate cancer cells, which exhibit castrate-resistant growth characteristics even though these cells were derived from a hormonally naïve patient." (PMID 20628607, 2010). "Our previous data demonstrated that AR suppressed c-Met transcription in LNCaP prostate cancer cells and castration of SCID mice bearing LNCaP xenografts induced c-Met expression in the tumors." (PMID 20946682, 2010). "This demonstrated that the overexpressed AR functions as a transcriptional factor in AR(+) cells similar to that in prostate cancer cells." (PMID 19816598, 2009). "In prostate cancer cell lines, there seems to be an inverse correlation between androgen receptor (AR) status and constitutive NF-κB activity." (PMID 19895686, 2009). "Longer polyglutamine tract length also results in decreased AR transcriptional activity in vitro, whereas shorter CAG repeats has been linked to increased activity and subsequent increased risk of prostate cancer." (PMID 19721807, 2009). "Similar to the AR in the prostate cancer cell line LNCaP, and as expected, the overexpressed AR in AR(+) cells treated with the synthetic androgen R1881 translocated from the cytoplasm to the nucleus." (PMID 19816598, 2009). "It has potent antitumour effects in vitro with the ability to effectively inhibit proliferation of a bicalutamide-resistant prostate cancer cell lines, which had increased AR expression." (PMID 19223900, 2009). "These include oestrogen, progesterone, glucocorticoid, and the adrenal hormone androst-5-ene-3β, 17β-diol (AED), a multi-potent hormone that is an androgen and oestrogen precursor, with the ability to directly transactivate AR and ER in prostate cancer cells." (PMID 19337256, 2009). "There are lines of evidence shown that RSV exerts its effects on prostate cancer in a AR-independent manner, due to the pivotal role of AR in prostate cancer development, special attention has been paid to the effects of RSV on AR." (PMID 19816598, 2009). "Out data provide a valuable data set in understanding the molecular basis for the growth prohibitive response program of the AR in advanced prostate cancers." (PMID 19668381, 2009). "It has been well established that the chemopreventive effects of RSV on prostate cancer involves its regulation of AR expression and function." (PMID 19816598, 2009). "Previous reports suggest that I3C is able to inhibit AR mediated proliferation of prostate cancer cells." (PMID 19909554, 2009). "There are data suggesting that the AR signaling is still functional in ‘hormone-refractory’ prostate cancer (HRPC)." (PMID 19668381, 2009). "When the same experiments were conducted with the prostate cancer LNCaP cells, in which the AR expression is affected by the intact AR promoter, both AR and PSA mRNA levels decreased." (PMID 19816598, 2009).
prostate carcinoma (continued). "The chemopreventive effects of resveratrol (RSV) on prostate cancer have been well established; the androgen receptor (AR) plays pivotal roles in prostatic tumorigenesis." (PMID 19816598, 2009). "Taken together, these observations highlight the function of β-catenin-independent Wnt signalling in the control of AR activity and provide one explanation for sFRP1 downregulation in prostate cancer." (PMID 19277043, 2009). "The androgen receptor (AR) is believed to participate in prostate cancer progression, including its activation and up-regulation, point mutations, and ligand-independent activation." (PMID 19171036, 2009). "Our data provide a valuable data set in understanding the molecular basis for growth inhibition response program of the AR in prostate cancer cells, which can be exploited for developing novel prostate cancer therapeutic strategies." (PMID 19668381, 2009). "Alterations in AR sequences and expression levels and perturbations in AR signaling networks have significant roles in the genesis and maintenance of prostate cancers (PCa)." (PMID 19668381, 2009). "Nonetheless, androgen receptor signalling remains active in castration-resistant prostate cancer despite these attempts at suppression." (PMID 19337256, 2009). "To summarise, we have shown that sFRP1 represses AR transcriptional activity and, as a result, inhibits proliferation of androgen-dependent prostate cancer cells and that the CRD is mainly responsible for both of these effects." (PMID 19277043, 2009). "It has been shown that inhibition of Erk1/2 activity in prostate cancer cell resulted in the reduction of AR gene expression." (PMID 19956729, 2009). "Here, we established for the first time a functional link between cystatin C and MAPK-Erk signalling and AR-mediated pathways in prostate cancer cells." (PMID 19956729, 2009). "It is well established that the chemopreventive effects of RSV on prostate cancer involve its alteration of AR expression and function." (PMID 19816598, 2009). "Because Frizzled-2 expression was relatively weak in the AR-expressing prostate cancer cell lines (22Rv1 and LNCaP), Frizzled-1, -3, -4 and -6 were chosen for the further analysis." (PMID 19277043, 2009). "In pathology, AR is one of the genes responsible for prostate cancer, which is the most frequently diagnosed cancer in men in the United States according to the American Cancer Society Statistics for 2008." (PMID 19503826, 2009). "Because sFRP1 is best known as a Wnt antagonist, it is plausible that it represses AR by sequestering endogenous Wnt ligands secreted by prostate cancer cells." (PMID 19277043, 2009). "AR gene amplification is found in one third of advanced prostate cancers and is believed to contribute to progression and metastasis of prostate cancer." (PMID 19956729, 2009). "The androgen receptor (AR) plays important roles in the development of male phenotype and in different human diseases including prostate cancers." (PMID 19668381, 2009). "AR plays pivotal roles not only in prostate cancer initiation, but also in its progression and even in the hormone-independent stages." (PMID 19816598, 2009). "Most so-called "androgen-insensitive" prostate cancers in fact retain high levels of AR expression and PSA continues to be expressed." (PMID 19691856, 2009). "The human prostate cancer cell-line LNCaP expresses a mutant androgen receptor that allows it to respond to a wide variety of hormones, including the adrenal hormone AED." (PMID 19337256, 2009). "It was shown to interact with Pim-1 kinase and be required for ligand-independent activation of androgen receptor in prostate cancer." (PMID 19765316, 2009). "The growth prohibitive properties of the AR or its response program can be exploited for developing novel prostate cancer therapeutic strategies." (PMID 19668381, 2009).
prostate carcinoma (continued). "Overexpression of AR is one of the mechanisms utilized by castration resistant prostate cancer cells, to overcome the growth inhibitory effects of hormone depletion therapy or other chemotherapy." (PMID 19956729, 2009). "We have investigated how the expression level of sFRP family members in prostate cancer cells affects AR signalling." (PMID 19277043, 2009). "We investigated the function of sFRP1 in androgen-dependent prostate cancer and found that sFRP1 inhibited androgen receptor (AR) transcriptional activity." (PMID 19277043, 2009). "For example, treatment of prostate cancers with di-hydrotestosterone induces acetylation at a lysine residue in the hinge region of the androgen receptor (AR) by the HATs p300, P/CAF, and TIP60." (PMID 19002169, 2009). "Androgen receptor signaling is critical to prostate cancer development as androgen receptors regulate the proliferation of prostate epithelial cells through several cyclin-dependent kinases." (PMID 19653896, 2009). "The androgen receptor (AR) is a member of the nuclear receptor superfamily, and is a key regulator of prostate cancer cell proliferation and survival." (PMID 19277043, 2009). "The androgen receptor (AR) is a steroid-activated transcription factor that binds at specific DNA locations and plays a key role in the etiology of prostate cancer." (PMID 18997859, 2008). "Having determined both the agonist and antagonist responses in the assay with wild type AR, we next wanted to examine the assay performance with an AR mutant relevant to prostate cancer." (PMID 18978937, 2008). "Of interest, two genes involved in prostate cancer progression, androgen receptor and AGR2, are increased in prostates of Ebp1 knock out mice." (PMID 19094237, 2008). "Our previous study revealed that Vav3 oncogene is overexpressed in human prostate cancer, activates androgen receptor, and stimulates growth in prostate cancer cells." (PMID 18518979, 2008). "In vitro, hydroxyflutamide activates AR transcriptional activity in the androgen-sensitive prostate cancer cell line, LNCaP." (PMID 18986533, 2008). "We determined the influence of the AR on the Wnt/β-Catenin transcriptional activity in prostate cancer cells with activated Wnt signaling under conditions that mimic the castration-resistant stage." (PMID 18218096, 2008). "On the other hand, the AR signaling was shown to repress β-Catenin/TCF mediated transcription induced by androgen in prostate cancer cells." (PMID 18218096, 2008). "Current therapy for advanced prostate cancer targets AR through the use of LHRH agonists and/or anti-androgens such as hydroxyflutamide or bicalutamide (Casodex)." (PMID 18978937, 2008). "Based on these results, we conclude that the AR can potentiate Wnt transcriptional activity in prostate cancer cells." (PMID 18218096, 2008). "The interaction between the AR and Wnt signaling provides a growth advantage to prostate cancer cells at castration levels of androgens." (PMID 18218096, 2008). "Vav1 functions as an oncogene involved in malignant transformation and the Vav family appears to play an essential role in angiogenesis and androgen receptor transcriptional activity in prostate cancer." (PMID 18925966, 2008). "Our results demonstrated a novel mechanism for the AR function by potentiating the Wnt signaling pathway to promote prostate cancer cell growth at the castration levels of androgens." (PMID 18218096, 2008). "Considering the important role of the AR in prostate cancer progression and possible regulation of AR expression by Ebp1, we deemed it necessary to evaluate the co-expression of Ebp1 with nuclear AR." (PMID 19025630, 2008). "Taken together, these results suggest that at castration levels of androgens, the amplified wild-type or mutant AR can synergistically interact with the Wnt signaling pathway, resulting in the stimulation of prostate cancer cell growth." (PMID 18218096, 2008).